PDHB (pyruvate dehydrogenase E1 subunit beta)
Diseases named in the same sentence as PDHB in open-access papers (continued):
Sharing a sentence is not in itself a finding about the gene and the disease.
cancer (27 papers, 2019 to 2025). A tumor composed of atypical neoplastic, often pleomorphic cells that invade other tissues. "PDHB encodes for a subunit of pyruvate dehydrogenase complex, which plays an essential role in metabolism and has been associated with cancer and neurological diseases." (PMID 37805522, 2023). "Based on the difference of PDHB mRNA expression in cancer and paracancer samples, we found that PDHB was significantly correlated with better OS, DSS and PFS in ccRCC." (PMID 37641032, 2023). "We first assessed the mRNA expression of PDHB in 33 human cancers and normal tissues using data from TCGA and GTEx datasets to investigate the potential involvement of PDHB in carcinogenesis and progression." (PMID 37641032, 2023). "The dysfunction of PDHB can lead to metabolism alteration which is one of the hallmarks of cancer cells." (PMID 36865349, 2023). "The differential expression analyses of OSCC tissues and para-cancer tissues demonstrated that LIAS and PDHB were suppressed in cancer tissues, but GLS and CDKN2A were accelerated." (PMID 35875097, 2022). "Prognostic analysis for OS, DSS, and PFS revealed that hypomethylation of DLAT, FDX1, MTF1, NLRP3, and PDHA1 was associated with low survival in most cancers, whereas hypermethylation of FDX1 and PDHB was associated with low survival in UVM(P < 0.05)." (PMID 36387247, 2022). "The mitochondrial version also shows increased conversion of pyruvate to acetyl-CoA in cancer cells through upregulation of PDHB and DLAT." (PMID 36282866, 2022). "Hypermethylated PDHB, LIPT1, LIAS and GLS were mainly associated with poor prognosis in cancer, whereas hypomethylated FDX1 was dominantly related to poor prognosis of LGG and ccRCC." (PMID 36581992, 2022). "LIAS and PDHB were cuproptosis promoters with low expression in cancer tissues, while GLS and CDKN2A were cuproptosis suppressors with high expression in cancer tissues." (PMID 35875097, 2022). "In this study, we performed a pan-cancer analysis of PDHB using the TCGA database." (PMID 37641032, 2023). "Moreover, murine models demonstrated that ectopic activation of the pyruvate dehydrogenase complex by exogenous expression of PDHB increased metastatic potential and survival of cancer cells." (PMID 37353799, 2023). "And we found that PDHB was lower expressed in a variety of cancers." (PMID 37641032, 2023). "In addition, the relative ratio of PDHB/PKM decreases in cancer tissues across different stages in comparison to the controls." (PMID 31071451, 2019). "In this pan-cancer analysis, we systematically profiled the expression and prognostic value of eight well-characterized cuproptosis-related genes—FDX1, LIAS, LIPT1, DLD, DLAT, PDHA1, PDHB, and SLC31A1—across 34 cancer types." (PMID 40601654, 2025). "Combined with 19 genes related to cuproptosis in the current cancer database, NFE2L2, PDHA1, PDHB, DLD, and GLS showed significant differences between the two groups." (PMID 38200445, 2024). "In Cuproptosis-related genes, SPC25 was positively correlated with GCSH, CDKN2A, PDHB, PDHA1, DLAT, DLD, and SLC31A1 of pan-cancer." (PMID 38605119, 2024). "A total of 6 CRSGs were screened out, including CDKN2A, GLS, FDX1, PDHA1, PDHB, and DLD; most of them have been reported in the direct regulation of cuproptosis and cancer progression." (PMID 37287976, 2023). "Most cancers show significantly lower mRNA levels in FDX1, DLD, DLST, LIAS, GLS, DBT, MTF1, and PDHB." (PMID 36209249, 2022). "The results showed that cuproptosis-related genes such as PDHB, PDHA1, DLAT, DLD, LIPT1 were significantly positively correlated with FDX1 in pan-cancer." (PMID 35991547, 2022). "The transcriptional levels of DLAT, FDX1, DBT, DLD, PDHB, and GCSH negatively correlate with methylation in part of tumors (> 7 cancer types)." (PMID 36209249, 2022). "We found that the expression of PDHA1, GLS, DLAT, PDHB and MTF1 were differed between cancer and paracancer." (PMID 36620594, 2022).
cancer (continued). "Furthermore, we compared the differential expressions of cuproptosis-related genes between OSCC tissues and para-cancer tissues and found that four genes (LIAS, PDHB, GLS, and CDKN2A) were differentially expressed." (PMID 35875097, 2022). "This could be corroborated by our proteomics functional analysis, where we found, for instance, a higher abundance of HADH, PLOD3 and ACAT1 (lysine degradation) and PFKL, NTRK1, PDHB and PDHA1 (central carbon metabolism in cancer) in control piglets compared to UL." (PMID 38409238, 2024).
infection (7 papers, 2015 to 2025). The state of being infected such as from the introduction of a foreign agent such as serum, vaccine, antigenic substance or organism. "Pgm and pgi gene were significant differential expressed in brain while pdhA, pdhB, pdhC and pdhD were significant differential expressed in spleen between two infection groups." (PMID 31449567, 2019). "Moreover, a 0.1 mM concentration of the PDHB inhibitor (OT) decreased infection-induced acetyl-CoA and downstream succinate production, which shifts host metabolism and leads to enhanced host cell survival." (PMID 34933448, 2021). "The pdhB mutant showed reduced growth in axenic medium during logarithmic phase, but was recovered in vivo from the udder and LNs of infected animals in the confirmatory screening experiment, indicating its relative survival in local sites of infection." (PMID 27765069, 2016). "We next tested the function of the PDHB inhibitor oxythiamine (OT), as well as its combination with IRAK1/4-Inh, in S. flexneri ΔvirG infection." (PMID 34933448, 2021). "Mitochondrial proteins are among these dually modified proteins, in agreement with our finding of infection-enhanced acetylations on TCA cycle proteins, including PDHB, DLAT, and DLD, at sites known as ubiquitinated." (PMID 30470744, 2018). "This was also evident from the calculated multiplicity of infection (MOI), which was found to be comparable for both the pdhB mutant and wild type PG2." (PMID 25799063, 2015).
peripheral neuropathy (2 papers, 2022 to 2023). A disorder affecting the peripheral nervous system. "In four patients, we identified four disease-causing genes, of which variants in PDHB, MTPAP, and SUCLA2 have been reported not as a cause of CMT but of other diseases associated with symptomatic or subclinical peripheral neuropathy." (PMID 35235001, 2022).
inflammation (1 paper, 2024). Aberrant reaction of the microcirculation characterized by movement of fluid and leukocytes from the blood into extravascular tissues. "Additionally, upregulated cuproptosis-related genes (LIAS and PDHB) were found to be positively associated with the occurrence of pulmonary inflammation in a septic mouse model." (PMID 39427197, 2024).
PDHB also shares sentences with these, for which no sentence is quoted: lung adenocarcinoma (3 papers); liver cancer (2); renal carcinoma (2); Alexander disease (1); Ataxia (1); bacterial infection (1); bladder cancer (1); bone cancer (1); brain cancer (1); cholangiocarcinoma (1); colon adenocarcinoma (1); congenital brain malformations (1); dementia (1); diabetic cardiomyopathy (1); epilepsy (1); eye cancer (1); gastrointestinal tumors (1); glaucoma (1); head and neck squamous cell carcinoma (1); head and neck tumor (1); hepatocellular carcinoma (1); kidney cancer (1); Leigh syndrome (1); leukemia (1); lung squamous cell carcinoma (1); lymphoid neoplasm (1); microcephaly (1); pancreatic cancer (1); Parkinson disease (1); periodontitis (1).
A further 7 diseases each share a sentence with PDHB in 1 paper.